ZEB1 (zinc finger E-box binding homeobox 1)
Diseases named in the same sentence as ZEB1 in open-access papers (continued):
Sharing a sentence is not in itself a finding about the gene and the disease.
cancer (continued). "Consistent with previous reports that EMT promotes stemness, the expression of a well-known cancer stem cell marker CD44 decreased upon Ovol2-induced transition to E and increased upon Zeb1/Snail-induced transition to M." (PMID 26554584, 2015). "Whole tissue sections from the same low-grade and high-grade budding cancers were immunostained for β-catenin, E-cadherin, CDX2, ZEB1 and ZEB2 and found to exhibit the expected protein phenotype." (PMID 25528769, 2015). "Of note, EMT plays a central role in cancer progression and can be promoted by KSHV through Notch-induced ZEB1, a transcription factor up-regulated in our dataset." (PMID 25942495, 2015). "One of the mechanisms through which E-Cadherin is downregulated in cancer cells is the transcription repression by Epithelial-mesenchymal transition (EMT)-related transcription factors, such as Snail, Slug and Zeb1." (PMID 25871391, 2015). "Many signals generated within the cancer microenvironment activate transcription factors considered to be promoters of EMT, such as SNAIL1, TWIST1 and ZEB1." (PMID 26362312, 2015). "Selective iNOS (1400 W) and pan-NOS (L-NMMA and L-NAME) inhibitors diminished cell proliferation, cancer stem cell self-renewal, and cell migration in vitro, together with inhibition of EMT transcription factors (Snail, Slug, Twist1, and Zeb1)." (PMID 25849745, 2015). "Expression of the nuclear factor ZEB1 induces EMT and confers a metastatic phenotype on carcinomas by repressing the E-cadherin gene at the transcriptional level." (PMID 26703648, 2015). "Expression of the nuclear factor ZEB1 has been demonstrated to induce EMT and confer a metastatic phenotype on carcinomas by repressing the E-cadherin gene at the transcriptional level." (PMID 26703648, 2015). "As shown, these miRNAs are active regulators of the expression of several cancer-related mRNAs, including ZEB1, ZEB2, VIM, VEGFA, NTRK3 and SPDEF, and most of the miRNAs are cancer-related." (PMID 24512620, 2014). "Of particular importance are ZEB1 and ZEB2, which are crucial regulators of EMT during cancer development." (PMID 25269476, 2014). "TGF-β-induced EMT can be suppressed by miR-147, independently of other miRs such as the miR-200 family members, through the translational inhibition of ZEB1 and the upregulation of CDH1 in cancer cells." (PMID 24454732, 2014). "ZEB1 and ZEB2 are key factors regulating CDH1 expression and their connection with EMT and metastasis of cancer cells has been well established." (PMID 24840099, 2014). "The miR200 by inhibiting the ZEB1 and ZEB2 proteins production induce the mesenchymal-to-epithelial transition in cancer cell lines and reduce their aggressiveness." (PMID 24933019, 2014). "The importance of the ZEB1 transcription factor, a known repressor of E-Cadherin, in promoting EMT and enrichment of cells with a cancer stem cell phenotype has been highlighted in recent publications." (PMID 23530113, 2013). "Both mesenchymal cancer cell lines formed predominantly mesenchymal-type tumors characterized by low E-cad and high ZEB1, while PC3-Epi tumors showed high E-cad and low ZEB1 expression." (PMID 24124593, 2013). "Following the knockdown of DCLK1, a significant downregulation of ZEB1, ZEB2, SNAIL and SLUG was observed following increased expression of pri-miR-200a in AsPC-1 cancer cells." (PMID 24040120, 2013). "The miR-200 family and miR-205 regulate EMT by targeting ZEB1 and ZEB2, which function as transcriptional repressors of E-cadherin expression, thereby reducing the aggressiveness of cancer cells." (PMID 23554909, 2013). "FGF2 has been shown to activate the MAPK/ERK pathway in various cancer cells, and we show in OVCAR-4 and SKOV-3 cells that ZEB1 expression is MAPK/ERK-dependent." (PMID 23554977, 2013). "In our model, we found that ZEB1 silencing resulted in MET induction and the upregulation of four TFs in mesenchymal cancer cells." (PMID 24124593, 2013).
cancer (continued). "Transcription factors of the Twist family (Twist1, Twist2), snail family (SNAI1/snail, SNAI2/slug), as well as ZEB family (ZEB1, ZEB2), control the EMT process in cancer." (PMID 24244294, 2013). "It is conceivable that Zeb1 during gastrulation also regulates other targets controlling cell behavior, as shown for specific laminin (LAMC2) and integrin (ITGB4) genes in cancer cells." (PMID 23667256, 2013). "While there is crosstalk among Snail family members and other transcription factors, including TWIST, ZEB1 and SIP1, knocking down Snail gene expression using RNA interference technology can effectively block cancer metastasis." (PMID 23516540, 2013). "In previous studies, miR-200a regulating the EMT process by targeting EMT-activating transcriptional factors ZEB1 and ZEB2 has been thoroughly elaborated in different types of cancers." (PMID 24260215, 2013). "Our findings strongly suggest that the TGF-b-induced EMT can be suppressed by miR-655, independently of miR-200 family members, through translational inhibition of ZEB1 and TGFBR2 in cancer cells." (PMID 23690952, 2013). "Our results suggest the potential of the EMT-suppressor miR-655 targeting ZEB1 and TGFBR2 as a prognostic marker and therapeutic agent for cancer." (PMID 23690952, 2013). "Thus, Zeb1 may play a key role in IL-1β-induced EMT in various cancer cells." (PMID 23174018, 2012). "TG2/NF-κB-induced HIF1 expression, in turn, was deemed necessary for high basal expression of the transcription repressors such as Twist, Snail, and Zeb1, the known inducers of EMT and stem cellness in cancer cells." (PMID 23185316, 2012). "Here, we show that ZEB1 represses CAR expression in both PANC-1 (pancreatic) and MDA-MB-231 (breast) human cancer cells." (PMID 21791114, 2011). "For instance, up-regulation of SNAIL1, ZEB1, ZEB2 or E12 in epithelial cells represses E-cadherin expression and induces EMT in several carcinomas." (PMID 21464926, 2011). "ZEB1 and the microRNA-200 family have been identified as central players in regulation of EMT, invasion and metastasis of pancreatic and other cancers." (PMID 24281177, 2010). "Of particular importance are ZEB1 and ZEB2 because they are crucial regulators of EMT during embryonic development and cancer." (PMID 20025777, 2009). "The profound morphologic changes and enhanced invasive capabilities of EMT in various cancers are thought to be regulated by several transcription factors, including SNAI1 (snail), SNAI2 (slug), and ZEB1 (δ-ef1)." (PMID 19087274, 2008). "Using additional Cre lines we provide evidence that myeloid ZEB1 exerts its anti-tumorigenic effect mostly via TAMs and not via cancer-relevant neutrophils, in which Zeb1 is expressed but has not been functionally investigated yet64–66." (PMID 40595293, 2025). "Notably, the expression of the standard isoform of CD44 was upregulated by ZEB1, and ERK activation was elevated in mesenchymal-like cancer cells." (PMID 40178908, 2025). "Research indicates that non-stem cancer cells can acquire stem-like characteristics mediated by factors such as ZEB1." (PMID 41013839, 2025). "Therefore, we measured the effect of sgRNAs for ZEB1 on CDS1 expression by qPCR and computationally scored the correlation between the expression of ZEB1 and CDS1 or CDH1 across cancer types in the DepMap." (PMID 40615674, 2025). "The upregulated ABCB1, ZEB1, and CD44 were engaged in microRNA regulation in cancer, SOX2 and KLF4 were engaged in pluripotency of stem cells, and TWIST1 and CD44 contributed to proteoglycans in cancer." (PMID 40251609, 2025). "Research indicates that non-stem cancer cells can develop stem-like characteristics influenced by factors like ZEB1." (PMID 41013839, 2025). "Regarding metastatic bladder cancer, GA directly targeted the key EMT regulator ZEB1 by upregulating miR-205-5p, which decreased ZEB1 protein expression, restored the E-cadherin/N-cadherin ratio, blocked the EMT pathway, and reduced cancer cell invasion and migration." (PMID 41311720, 2025).
cancer (continued). "However, in malignant tumors with reserved prognosis, ENO1 showed moderate staining in approximately 50% of samples (E, F) and strong in the other 50% (A, C), while ZEB1 showed consistently strong intensity." (PMID 40005870, 2025). "First, we found that ZEB1, SNAI1, SNAI2, TWST1, SMAD3, and HIC1, known to be affected upon EMT in both the RPE and forms of cancer, are preferential repressors in hiPSCs compared to RPE, likely acting as preventive developmental gatekeepers under physiological conditions." (PMID 40565279, 2025). "Additionally, numerous factors are involved in the cancer plasticity-mediated therapy resistance, such as transcription factors like SOX2 or ZEB1." (PMID 41190163, 2025). "ZEB1 and ZEB2 are known for their ability to stimulate EMT, but some reports indicate that they can have both redundant and opposing functions, even in the same type of cancer." (PMID 41303618, 2025). "The radioresistance mechanism regulated by ETV1 could involve ZEB1 whose expression is controlled by ETV1 and which is at the crossroads of EMT, metastases and resistance to therapy, including radiotherapy for many cancers." (PMID 40275610, 2025). "ZEB1 is a known key player in EMT activation and as a valid marker for cancer stem cells." (PMID 40830586, 2025). "ZEB1 drives EMT and confers chemotherapeutic resistance in cancer cells." (PMID 40133270, 2025). "In ESCC, miR-200b suppresses cell growth and induces cell cycle arrest by modulating expression of cell cycle regulator genes and the Wnt/β catenin signaling pathway, and the miR-200 family post-transcriptionally suppresses ZEB1 and ZEB2, which are crucial EMT activators in various types of cancers." (PMID 40529228, 2025). "Moreover, TNF-α enhances the invasive characteristics of cancer cells through the induction of EMT, which is mediated by mechanisms dependent on Snail or ZEB1/ZEB2." (PMID 39941858, 2025). "Furthermore, in CAFs, LPA production leads to high expression of zinc finger E-box-binding homeobox 1 (Zeb1) through LPAR1 and 3/Gi/Rho signalling to promote expression of AREG, resulting in enhanced cancer invasiveness." (PMID 38607068, 2024). "Snail, Slug, ZEB1, and Twist are only a few EMT-TFs that may suppress E-cadherin expression and increase cancer cell motility and invasiveness." (PMID 38431604, 2024). "This fluidity is further supported by studies showing non-stem cancer cells’ ability to acquire stem-like traits, a transformation driven by factors like ZEB1, a key EMT player." (PMID 38329598, 2024). "Furthermore, the ZEB1/NuRD(MTA1) complex was confirmed to regulate glycolysis and promote invasiveness of cancer cells, suggesting that the NuRD complex plays a role in glycolysis and cancer progression in CRC." (PMID 39193340, 2024). "The ZEB1 protein is a key transcription factor in inducing EMT and cell plasticity in cancer cells." (PMID 38469234, 2024). "Further analysis of differences in the expression of ZEB1, ZEB2, and CREB3L1, which are included in the GeoMx Cancer Transcriptome Atlas Panel gene list, revealed significant enrichment in Vim+ carcinoma cells relative to that in Vim− carcinoma cells from the nine ROIs." (PMID 39256881, 2024). "The analysis of the tumoral markers p27, CD44, Fibulin-3, and NANOG and the expression of genes related to cancer transformation such as NANOG, CDH-1, and Zeb-1 showed that the simulated microgravity environment led to expression patterns in MeT-5A cells similar to those observed in BR95 cells." (PMID 39451527, 2024). "Our observation of high ZEB1 expression in the HM cells aligns with previous findings of elevated ZEB1 expression in cancer cells lacking morphological indicators of complete EMT." (PMID 39256881, 2024). "Since TGF‐β promotes anchorage‐independent growth of cancer cells, it remains unclear why ZEB2 promotes proliferation in soft agar to a greater extent than ZEB1." (PMID 39362647, 2024).
cancer (continued). "In fact, it appears able to inhibit the EMT process by regulating HIF1α expression, or through transcriptional repression of SNAIL1, ZEB1 and VEGF in colon, oral and neck tumours, and to repress EMT in pancreatic ductal adenocarcinoma cells sensitizing cancer cells to chemotherapy." (PMID 38773406, 2024). "As a member of the zinc finger E-box (ZEB) family of transcription factors, ZEB1 plays a crucial role in regulating cell differentiation, especially in controlling epithelial-mesenchymal transformation (EMT), which is vital for cancer progression." (PMID 38613804, 2024). "ZEB1 and CD47 were colocalized within hypoxic cancer cell islets." (PMID 38183060, 2024). "Moreover, a heatmap depicting ZEB1, ZEB2, CREB3L1, and CDH1 across the nine ROIs revealed clear segregation between Vim+ and Vim− carcinoma cells." (PMID 39256881, 2024). "ZEB1 is a pivotal member of the ZEB family of transcription factors, playing a crucial role in regulating key molecular pathways in malignant cells at the invasive front of carcinomas." (PMID 39736693, 2024). "Several transcription factors (TFs) mediate the development of EMT, including SNAIL1/SNAIL2, TWIST1/TWIST2 and ZEB1/ZEB2, which are overexpressed in various carcinomas along with the under expression of the metastasis suppressor Raf Kinase Inhibitor Protein (RKIP)." (PMID 39335152, 2024). "ZEB homeobox is a transcription factor family that includes ZEB1 and ZEB2, which may induce the EMT during cancer development." (PMID 37416766, 2023). "Importantly, GAS41 has been found to target downstream regulators such as Zinc finger E-box-binding homeobox 1 (ZEB1), transforming acidic coiled-coil 1 (TACC), and (Transcription elongation factor A protein 1) TCEA1 to modulate cancer progression." (PMID 37853482, 2023). "ZEB1 and ZEB2 can induce EMT leading to cancer cell migration, invasion, and metastasis." (PMID 37770496, 2023). "Cancer cells with a mesenchymal state that usually become resistance to conventional therapies (i.e., apoptosis inducers) are strongly dependent on GPX4, which is related to upregulated expression of zinc finger E-box binding homeobox 1 (ZEB1)." (PMID 37795022, 2023). "The expression of ZEB1 in (cancer) cells is regulated by several positive and negative signaling pathways and regulatory networks." (PMID 38139138, 2023). "Thus, by upregulating both ZEB1 and YAP1, cancer cells are triggering a program that facilitates cancer progression and invasion while still maintaining epithelial markers." (PMID 36936987, 2023). "Moreover, this transcriptome reprogramming was accompanied by significant increase in ZEB1, ZEB2 and TWIST2 EMT-TFs in cancer cells." (PMID 36936987, 2023). "In addition, β-catenin translocates into the nucleus and activates the expression of ZEB1, whereas Wnt signaling and E2F1 upregulate ZEB2 expression, resulting in EMT activation and cancer progression." (PMID 37444447, 2023). "The transcription factor ZEB1 (Zinc finger E-box-binding homeobox 1) plays a specific and crucial role in promoting epithelial-mesenchymal transition (EMT), a cellular process that occurs in embryonic development, tissue repair, and cancer progression." (PMID 37469704, 2023). "In cancer cells, ERK5 either promotes or inhibits SNAIL function, although ERK5 activation usually promotes EMT by increasing the function of SLUG, ZEB1, and ZEB2." (PMID 37009481, 2023). "Increasing evidence suggests that EMT-inducing transcription factors (EMT-TFs), Snail, Slug, ZEB1 and Twist, downregulate E-cadherin expression and further promote the EMT process, which results in cancer cells losing epithelial properties but acquiring mesenchymal properties." (PMID 37853437, 2023). "ZEB1 and ZEB2 overexpression has been found in several human cancers, including NSCLC." (PMID 36376711, 2023).
cancer (continued). "Moreover, the EMT-inducing transcriptional repressor ZEB1 can function as a transcriptional coactivator of YAP, integrating Hippo signalling and EMT processes with similar cancer-promoting effects." (PMID 37414748, 2023). "We then explored by real-time qPCR the impact of miR-662 overexpression in MDA-MB-231 cells on expression levels of well-established stemness markers that are involved in embryogenesis and cancer –NOTCH1, WNT7b, ZEB1, TCF3, CTNNB1, CD44, CD24, SNAI2, OCT-04, c-MYC, EZH2–." (PMID 37443350, 2023). "Several non-coding RNAs were found to target ZEB1 and ZEB2 translation in various cancer types." (PMID 37927751, 2023). "Interestingly, these findings suggest a degree of overlap between regulators of EMT and focal adhesions; specifically, ZIP4 and ZEB1 play important roles in promoting both EMT and cancer cell migration and invasion." (PMID 37046830, 2023). "It has been found recently that human SLFN5 can inhibit ZEB1 transcription by directly binding to the SLFN5 binding motif on the ZEB1 promoter, thereby maintaining the epithelial cell morphology and inhibiting metastasis in BRCA mutant cancer cells." (PMID 35216035, 2022). "ZEB1 inhibits the epithelial splicing regulatory protein 1 (ESRP1), triggering a change from the epithelial-specific CD44v isoform to the standard CD44s isoform, which maintains the stemness and mesenchymal characteristics of cancer cells." (PMID 35454770, 2022). "Studies have shown that ZEB1 and SIP1 are key promoters of cancer progression." (PMID 36447214, 2022). "Herein, we identified a correlation between ZEB1 and ZEB2 in various cancers." (PMID 35723302, 2022). "ZEB1, the member of the ZHF family, could regulate the expression of multiple oncogenes, thereby promoting the initiation and development of cancer." (PMID 35483343, 2022). "The KEGG pathway data showed the involvement of ZEB1 and RECK in microRNA networks in cancer." (PMID 35098570, 2022). "Finally, by considering the genes recapitulating IL-3 biological functions, we proposed a model, including IL-3Rα, SNAI1, ZEB1, VIM, CTNNB1, MMP2, SPRY2, and CD274, that remarkably discriminates cancer aggressiveness (AUC = 0.86 95% CI = 0.82–0.89)." (PMID 36010912, 2022). "Both ZEB1 and ZEB2 induce EMT and enhance cancer progression." (PMID 35723302, 2022). "Interestingly, these findings revealed that ZEB1 and ZEB2 were positively correlated in all cancer types." (PMID 35723302, 2022). "Specifically, it has been demonstrated that NUCB2 contributes to cancer metastasis and a number of related processes, including EMT, endoplasmic reticulum (ER) stress, and cancer anorexia-cachexia syndrome, through regulation of the LKB1/AMPK/TORC1/ZEB1 and Akt/mTOR pathways." (PMID 36585713, 2022). "While both EMT and ZEB1 has been found to medicate acquired resistance to EGFR inhibitors in non-small cell lung cancer, our iGenSig signature suggested the discordance of ZEB1 overexpression with EMT induction and their differential contribution to Erlotinib resistance in Pan-cancer cell lines." (PMID 35618721, 2022). "However, direct linking is quite likely because data on direct interactions of miR-203 with ZEB1 and ZEB2 in other cancer types were obtained, as cited above." (PMID 35163224, 2022). "In a mouse pancreas cancer model, cancer aggravation, including tumor differentiation, invasion, and metastasis, is not affected by genetic SNAIL depletion, but is reduced by genetic depletion of ZEB1." (PMID 36140527, 2022). "The detailed mechanisms of ZEB1 and ZEB2 in cancer should be elucidated." (PMID 35723302, 2022). "Among the selected cancer stemness genes, we found that TERT, MYC, CD44, BMI1, ABCB1 and ABCG2 were highly expressed in OCM1 cells compared to their expression in C918 cells, whereas the expression of ZEB1 was opposite to that of the stemness genes." (PMID 35404029, 2022).